IL6 (interleukin 6)
Diseases named in the same sentence as IL6 in open-access papers (continued):
Sharing a sentence is not in itself a finding about the gene and the disease.
tumor (continued). "In tumor microenvironment, IL-6 interacts with its receptor and associates with the target cell membrane glycoprotein 130, inducing pro-inflammation cytokines production to support the chronic inflammation." (PMID 32655554, 2020). "IL-6 produced by tumor-associated macrophages (TAMs) can activate the STAT3 signaling pathway to promote CD44+ LCSCs." (PMID 33117795, 2020). "IL-6 overproduction in patients with CD is linked to the production of inflammatory cytokines and has a role in tumor angiogenesis, which makes it potential for IL-6 targeted therapy." (PMID 32399323, 2020). "High reactive oxygen species (ROS) associated within tumor microenvironments and IL-6 induce TIPE2 in myeloid precursors." (PMID 33519825, 2020). "Interleukin-6 (IL-6) is a hallmark of a wide range of biological functions, including immune regulation, hematopoiesis, inflammation and tumor development." (PMID 32041604, 2020). "Polarization of Th17 and related cytokines including 1L-17A, IL-17F, IL-21, IL-22, TNF-α, and IL-6, in CRCs is associated with tumour promoting inflammation, immunosuppression, induction of pro-angiogenic factors, and poor patient outcome." (PMID 32635383, 2020). "A strong positive association between the serum IL-6 and the progression and poor prognosis of tumors in patients with several types of tumor was already found." (PMID 32819324, 2020). "IKRAS mice presented increased progression to high-grade PanINs, higher tumor cell proliferation rate and prolonged survival, compared to mice with IL-6 deficiency." (PMID 32659999, 2020). "On the other hand, the expression of inhibitory molecules such as CTLA4, PD-1, and LAG3 on CD8+ T cells are promoted by IL-6 and IL-10, that produced by tumor cells and tumor-associated macrophages, in turn inhibit CD8+ T cells infiltration." (PMID 32208363, 2020). "Enhanced IL-6 levels in tumor tissues or serum are associated with aggressive tumor phenotypes and poor survival in different types of cancer, including prostate cancer." (PMID 32528731, 2020). "We also determined the serum concentration of the common tumor-promoting cytokines (IL-6, VEGF, TGF-β, and TNF-α) using the enzyme-linked immunoassay (ELISA) in samples from the same patients with miRNA validation." (PMID 33125430, 2020). "IL-6 secreted by endothelial cells within the prostate TME are also capable of promoting tumor invasiveness and metastasis via MMP9 activation by causing tumor remodeling." (PMID 32585812, 2020). "Berberine reduces protein levels of the STAT3 in nasopharyngeal carcinoma cells and blocks STAT3 activation induced by IL-6 secreted by tumor-associated fibroblasts." (PMID 33198257, 2020). "Both IL-6 and integrin β6 expression were associated with poor tumor differentiation and advanced N stage and TNM stage." (PMID 32855767, 2020). "Such a tumor can be associated to an inflammatory Castleman-like syndrome, due to a secretion of interleukin-6 (IL-6)." (PMID 32244473, 2020). "Tumor-associated efferocytic macrophages are typically M2 polarized pro-inflammatory macrophages that promote cell growth through the production of IL-6, IL-23, and TNFα." (PMID 32059476, 2020). "Tumor-associated macrophages (TAMs) are a major component of tumor immune cell infiltrates, and are a major source of IL-6 and TNFα in the TME." (PMID 32317968, 2020). "Our results from RNA-Seq analysis suggested that genes associated with HDAC activation and IL-6 signaling pathway were upregulated in tumor-infiltrating I-MDSCs, compared to those isolated from NT." (PMID 31941522, 2020). "Regarding the role of TME in a tumor, the major IL-6-producing cancer-associated fibroblasts (CAFs) promote cancer stemness and induce an immune adaptive inflammatory response, thus favoring CRC progression." (PMID 32855767, 2020).
tumor (continued). "This cytokine is a hallmark of inflammation and, similarly to IL-6, plays a dual role in the tumor immunology." (PMID 31105699, 2019). "Tumor-associated macrophages (TAM) release IL6, which activates the IL-6 receptor (IL6R)/STAT3 pathway in CRC cells." (PMID 31885581, 2019). "There is a positive correlation between IL-6 trans-signaling-induced autophagy in the tumor and weight loss." (PMID 30678689, 2019). "CXCL5/ENA-78 and IL-6 are cytokines that have been associated with tumour progression and have therefore the potential to cause serious side effects." (PMID 31010082, 2019). "Evidence highlighting the anti-tumor role of IL-6 associated with maneuvering of T-cell immunity has come up." (PMID 31769418, 2019). "As an essential element of inflammatory response, IL-6 is one of the best characterized protumorigenic cytokines; it was not only involved in immune regulation but also associated with tumor immune microenvironment." (PMID 31781194, 2019). "The inflammatory microenvironment of a tumor is caused by inflammatory cytokines including IL-1β, IL-6 and TNF-α." (PMID 30791624, 2019). "IL-6 is an anti-inflammatory cytokine that is strongly implicated in tumor progression in numerous cancer types." (PMID 31361777, 2019). "Within the tumor microenvironment, IL-6 is secreted by tumor associated macrophages (TAMs), T-cells, fibroblasts, and malignant cells (i.e., cancer cells)." (PMID 31174326, 2019). "Inflammatory markers, such as interleukin-6 (IL-6), have been associated with both the malignant transformation of epithelial cells and tumor progression, thus linking low-grade inflammation with a higher risk of cancer and recurrence in the survival phase." (PMID 31414667, 2019). "Tumor secrets various immune suppressive cytokines such as VEGF, IL-6, and IL-10 to promote the accumulation of heterogeneous populations of tumor associated macrophages (TAMs), myeloid-derived suppressor cells (MDSCs), and regulatory T cells." (PMID 31639056, 2019). "MiR155 contributes to impaired T cell-dependent antibody response, promotes production of both monocytic and granulocytic MDSCs and induces chemoresistance through C/EBPβ/IL6/IL6R/STAT3 signaling axis in tumor-associated macrophages." (PMID 30925928, 2019). "Adipocytes produce pro-inflammatory adipokines and cytokines [including CCL2, interleukin-6 (IL-6), and TNFα], which increase inflammation and metastatic risk, supporting tumor survival." (PMID 31788448, 2019). "miR-369-5p is associated with tumor migration, whereas miR-151-3p inhibits lipopolysaccharide (LPS)-induced IL-6 production by targeting STAT3." (PMID 31694199, 2019). "A strong association was observed between high ACTA2/IL6 mRNA co-expression and tumor invasiveness (****P < 0.0001), correlating with our in vitro findings." (PMID 30744595, 2019). "NF-κB and STAT3 can enhance the expression of IL-6, creating a feed-forward loop implicated in tumor development, progression, and metastasis." (PMID 31557902, 2019). "Our present findings confirm that vincristine stimulates the secretion of tumor growth factors class beta and interleukin-6 from cancer-associated fibroblasts as a result of paracrine stimulation by cancer cells." (PMID 31010006, 2019). "IL-6 peak is associated with the worst prognosis because it is related both to tumor stage and time to RT response." (PMID 30658426, 2019). "Similar to TAMs, it is likely that MDSCs are stimulated by a variety of soluble factors, such as GM-CSF, VEGF, TNF-α, PGE2, IL-1β, IL-6, and IL-10, which are secreted by tumor and infiltrating immune cells, as well as tumor-associated fibroblasts." (PMID 31428574, 2019).
tumor (continued). "In our data, we found the CD68+IRF8+, CD68+CD206+, and CD68++CD163+ macrophages to be co-localized in the same tumor and were correlated with the increase of IL-1-, IL-6-, and IL-10-associated pathways, respectively." (PMID 31477692, 2019). "IL17A-mediated induction of IL-6 and Granulocyte-colony stimulating factor (G-CSF) expression in the tumor cells has been shown to recruit tumor-associated neutrophils (Ly-6G+)." (PMID 31921642, 2019). "The proinflammatory cytokines, such as TNF-α and IL-6, promote the generation of free radicals causing damage to DNA, that cause genetic mutations and finally lead to tumor initiation." (PMID 31450710, 2019). "In cancer patients, IL-6 induces development and immunosuppressive function of MDSCs and tumor-associated macrophages through signal transducer and activator of transcription 3 (STAT3)-mediated mechanism." (PMID 31013891, 2019). "IL-6 is a pleiotropic cytokine that has been implicated in proliferation and survival of tumor cells." (PMID 31523190, 2019). "The presence of this iCAF subset, characterized by high expression of IL-6 and IL-8, is associated with poor prognosis in both tumor types." (PMID 31731701, 2019). "The data demonstrated that enhanced expression of IL-6 was correlated with clinical tumor burden and the risk of biochemical failure." (PMID 31315262, 2019). "Few groups investigated salivary IL-6 expression in association with various tumor stages and differentiation grades." (PMID 31766212, 2019). "Surprisingly, this study also showed that 6-OHDA treatment reduced tumor-associated macrophages, as well as tumor IL-6 production." (PMID 31822725, 2019). "By contrast, HCCs cotransplanted with IL-6-deficient HSCs reduced the tumor area from 42.6% to 22.2% compared with HCCs cotransplanted with wild-type HSCs (22.2% ± 3.9% vs. 42.6% ± 5.1%, p < 0.05)." (PMID 31614930, 2019). "ER-negative breast cancers produce more IL-6 than ER-positive breast cancers, and the high expression of IL-6 is linked with higher tumor grades and stages." (PMID 31252615, 2019). "Shining light on the role of IL6 in cancer cachexia, recent work demonstrated that the elevated IL6 in cachexia-associated tumor models suppresses hepatic ketogenesis, by downregulating expression of master ketogenic regulator PPARα in the liver." (PMID 31058816, 2019). "The number of MDSCs within the liver tumor area was higher in three HCC-bearing mice, namely those bearing HCCs alone, HCCs cotransplanted with HSCs, and HCCs cotransplanted with IL-6-deficient HSCs, compared with non-tumor-bearing mice (sham group)." (PMID 31614930, 2019). "Of note, IL-6 levels were significantly associated with EB extension (localized or generalized disease), disease severity and anti-skin antibodies levels." (PMID 31739489, 2019). "Loading STAT3 siRNA on lipid-substituted PEI is associated with decreased viability and proliferation of tumor cells by upregulation of caspase-3 and IL-6, and down-regulation of STAT3 and VEGF." (PMID 31569687, 2019). "Further, by inhibiting transcription in the tumour associated macrophages, lurbinectedin downregulates immune-suppressive cytokines such as interleukin-6 (IL-6), interleukin-8 (IL-8), C-C motif chemokine 2 (CCL2) and VEGF." (PMID 31619019, 2019). "An important cellular source of IL-6 appear to be the tumor-associated macrophages, although HCC cells themselves are also able to secrete IL-6 in a YAP-dependent manner." (PMID 31683891, 2019). "Even though in our study the expression of IL-6 was associated with better survival, its overexpression is associated with tumor growth, progression and response to therapy in many types of cancer 77-80." (PMID 31602271, 2019). "In ovarian cancer patients, cisplatin administration increases IL-6-producing myofibroblastic CAFs populations through activation of NFκB signal pathway in the tumor-associated stroma." (PMID 31067787, 2019).
tumor (continued). "Of these cytokines, IL-6 in particular acts to increase the synthesis of acute-phase proteins, and have shown to be associated with both adverse prognosis and tumor stage in several types of cancers." (PMID 30621619, 2019). "Significantly, the GBM cohorts harboring a high-level H2AFJ transcript combined with high-level expression of TNF-α/NF-κB geneset, IL-6/STAT3 geneset or HADC3 were associated with a shorter time to tumor repopulation after initial treatment with TMZ." (PMID 31906036, 2019). "IL-6, either secreted by tumor or tumor-associated cells, mediates resistance to 5-fluorouracile in colon cancer cells." (PMID 31117237, 2019). "TNF is implicated with cellular proliferation in hepatocarcinogenesis and persistent IL-6 is associated with tumor development." (PMID 30606143, 2019). "A number of inflammatory mediators including the cytokines TGFβ, TNFα, IL-1, IL-6, and IL-8, and several chemokines produced by the tumor-associated cells are also EMT-inducers, leading to inflammatory cytokine-induced EMT (ICI-EMT)." (PMID 31557902, 2019). "In SKOV-3 cells, PD-L1 was variably found in the surface and cytoplasm, and its expression was correlated with high levels of TNF-α, IL-10, and IL-6 released from tumor-associated macrophages (TAMs)." (PMID 31861351, 2019). "These cancer-associated fibroblasts (CAFs) produce IL-6, which promotes tumor growth by stimulating angiogenesis, cancer cell proliferation, and invasion." (PMID 31277406, 2019). "Although not all NSCLC patients with low-muscularity were cachectic, the tumor gene expression profile identified molecules, such as IL-6 and IL-8, consistently linked to inflammation and cancer cachexia pathogenesis." (PMID 31455042, 2019). "In terms of a potential cancer therapy, inhibition of the strongly pro‐inflammatory SASP is likely to be a considerable advantage, since pro‐inflammatory signalling, through IL‐6 in particular, has been linked to tumour progression and metastasis." (PMID 31148378, 2019). "This enhanced tumor growth elicited by IL-17 was associated with increased expression of IL-6 and also macrophage recruitment at the tumor site." (PMID 31284453, 2019). "In this study, we examined the dietary antioxidant capacity and plasma IL-6 level, one of the major tumor-promoting cytokines, regarding risk of CRC." (PMID 31795177, 2019). "This review showed that a large number of pro-inflammatory ILs (IL-1, IL-6, IL-8, IL-11, and others) generated by host immune cells and/or tumor cells are linked with tumor aggressiveness, as confirmed by numerous preclinical studies." (PMID 31847214, 2019). "IL-6 level was well correlated with tumor stage and undetectable IL-17A was associated with extrahepatic metastasis." (PMID 30824840, 2019). "Reductions in tumor volume were associated with natural killer cell infiltration into the tumors, which was dependent upon the release of interleukin-6 (IL-6) from contracting skeletal muscle." (PMID 31244666, 2019). "In BC patients, plasma and tissue IL-6 levels are elevated and associated with tumor progression and poor prognosis." (PMID 29454317, 2018). "Increased levels of NE and E enhance the gene expression of VEGF, IL-6, and MMPs, molecules which are linked to tumor progression in HNSCC and other cancers." (PMID 30125310, 2018). "IL-6 is a pleotropic cytokine associated with several aspects of tumour progression including EMT, stemness, angiogenesis and therapeutic resistance." (PMID 29891854, 2018). "The end targets of this pathway, IL-6, IL-1α and IL-1β, and IL-8 cytokines, presented increased expression in the mesenchymal subtype, and they have also been associated to tumor malignancy and tumor cell migration." (PMID 29912993, 2018). "Tumor-associated macrophages exacerbate tumor progression via the secretion of several cytokines such as interleukin-1β and interleukin-6." (PMID 30497501, 2018).
tumor (continued). "The regulation of IL-6 expression in the tumor-associated microenvironment has been studied for many years, and multiple mechanisms have been identified, including genetic and epigenetic regulation." (PMID 30266897, 2018). "In malignant diseases, the production of IL-6 by cancer-associated fibroblasts contributes to tumour–stroma interactions that are involved in many processes, including angiogenesis." (PMID 29772648, 2018). "IL-6 is overexpressed in tumor microenvironment, in which tumor surrounding adipocytes are referred as cancer-associated adipocytes." (PMID 30013512, 2018). "Regarding different OC cell lines (OVCAR3, SKOV3, A2780), the TLR4 activation induced IL-1 receptor-associated kinase (IRAK)-4 and NF-kB signaling, and c-Jun, IL-6 and IL-8 production, all of which related to tumor chemoresistance." (PMID 29343281, 2018). "This cytokine is considered a key link between inflammation and tumor genesis due to the confirmed association of IL-6 expression and CRC prognosis, as well as association with IBD." (PMID 30154846, 2018). "IL-6 upregulates the expression of MMPs (1, 2, and 9), thereby increasing cell migration and tumor metastasis; while IL-8 has been implicated in the upregulation of MMP 2 and mediation of MMP-9 release, which correlates with high-grade and invasive tumors." (PMID 30220965, 2018). "In recent years, numerous experiments have confirmed that the abnormal expression of IL-6 and its receptor is associated with the pathogenesis of tumor and is related with the diagnosis, prognosis, and treatment of tumor." (PMID 30671125, 2018). "EHF also represses IL-6 in prostate epithelial cells by directly binding the IL-6 promoter, and EHF loss drives tumour progression by de-repression of IL-6, and subsequent stimulation of STAT3 signaling." (PMID 30200227, 2018). "Consistent with increased level of SASP-associated GATA4, we observed upregulation of IL-6 at the first two time points and in the primary culture obtained in the progressing tumor." (PMID 29527515, 2018). "IL-6 is capable of modulating diverse cell functions such as inflammatory reactions, and is implicated in the regulation of tumor growth and metastatic spread in different cancers." (PMID 30587810, 2018). "Cooperate with tumor-associated macrophages (TAMs), TINs can produce IL-6 and granulocyte colony-stimulating factor, activate the STAT3 signaling pathway to slow down neutrophil degranulation and enhance tumor proliferation." (PMID 30103707, 2018). "While the accumulation of MDSC in inflammatory states was initially associated with increased TNFα and IL-6 levels, more recent data suggest that increased TNFα expression in the tumor microenvironment reduces MDSC infiltration and supports tumor regression." (PMID 29632539, 2018). "The role of TNFα and IL-6 as master regulators of tumor-associated inflammation and tumor-promoting functions makes them promising targets for adjuvant anti-cancer therapy." (PMID 29946544, 2018). "The increase in IL6 levels in CRPC tumours is closely associated with a systemic rise in circulating IL6." (PMID 29540470, 2018). "Monoclonal antibodies directed against TNF-α, VEGF, and IL-6 has shown promising results to ameliorate inflammation and cancer, while direct administration of IL-2 has been shown to cause tumor regression." (PMID 29662489, 2018). "Another possibility is that systemic IL-6 in NOG-hIL-6 Tg mice predisposes human macrophages to differentiate into TAM-like cells upon exposure to stimuli from the tumor microenvironment." (PMID 29456539, 2018). "Flow cytometry analysis of tumor-associated F4/80+ macrophage cells show that indicated that IL-6 knockout robustly decreased CD86−CD206+ macrophage population and slightly increased CD86+CD206− macrophage population." (PMID 29422647, 2018).